OR5AU1 (olfactory receptor family 5 subfamily AU member 1)
Description:
Odorant receptor.
Synonyms: OR14-38
Tractability: Antibody: UniProt places it where antibodies can reach, with medium confidence; UniProt predicts a signal peptide or a membrane-spanning region; its Gene Ontology location is reachable by antibodies, with medium confidence. PROTAC: ubiquitination databases record sites on it.
Gene: Protein-coding gene on chromosome 14 (21,148,370 to 21,159,060, reverse strand). Ensembl gene ENSG00000169327.
Subcellular location: Cell membrane
Pathways (Reactome):
Sensory Perception: Expression and translocation of olfactory receptors
Gene Ontology:
Molecular function: odorant binding; olfactory receptor activity; G protein-coupled receptor activity
Biological process: sensory perception of smell; detection of chemical stimulus involved in sensory perception of smell; G protein-coupled receptor signaling pathway
Cellular component: plasma membrane; membrane
Genetic constraint (gnomAD): Loss-of-function variants: 2 observed, 2.02 expected, observed/expected ratio (o/e) 0.99, 90% interval 0.36 to 1.88. That is too few expected variants to judge how well the gene tolerates losing a copy. Missense variants: 415 observed, 394.06 expected, observed/expected ratio (o/e) 1.05, 90% interval 0.97 to 1.14. Synonymous variants: 169 observed, 161.2 expected, observed/expected ratio (o/e) 1.05, 90% interval 0.92 to 1.19.
Homologues: Orthologues: chimpanzee OR5AU1 (98% identical), pig OR5AU1 (89% identical), rat Or5au1 (87% identical), mouse Or5au1 (84% identical), tropical clawed frog or5dd2b (48% identical). Paralogues in human: OR8D1 (54% identical), OR5B12 (54% identical), OR5AP2 (54% identical), OR5AR1 (53% identical), OR5B21 (52% identical), OR8D4 (52% identical), OR5A1 (51% identical), OR5AS1 (51% identical), OR5F1 (51% identical), OR9I1 (51% identical), OR5B3 (51% identical), OR5I1 (51% identical), and 84 more.
Diseases named in the same sentence as OR5AU1 in open-access papers:
OR5AU1 is named in the same sentence as 1 disease in open-access papers, as found by Europe PMC text mining. Sharing a sentence is not in itself a finding about the gene and the disease. The quoted sentences say what the papers report.
breast carcinoma (1 paper, 2019). "Nearly 50% of the cell lines in group II with upregulation of OR5AU1 were not classified among the most common human breast cancer phenotypes (NA)." (PMID 31551495, 2019).